SAMD10 (sterile alpha motif domain containing 10)
Synonyms: C20orf136; dJ591C20; dJ591C20.7
Tractability: PROTAC: its protein half-life has been measured.
Gene: Protein-coding gene on chromosome 20 (63,974,116 to 63,980,008, reverse strand). Ensembl gene ENSG00000130590.
Subcellular location (Human Protein Atlas): Nucleoplasm
Gene Ontology:
Biological process: cell surface receptor protein tyrosine kinase signaling pathway
Cellular component: cytoplasmic side of plasma membrane
Genetic constraint (gnomAD): Loss-of-function variants: 16 observed, 20.78 expected, observed/expected ratio (o/e) 0.77, 90% interval 0.52 to 1.17. The upper end of that interval is the gene's LOEUF score, 1.17, which puts it in group 5 of 6, group 1 being the genes least tolerant of losing a copy. Missense variants: 227 observed, 257.1 expected, observed/expected ratio (o/e) 0.88, 90% interval 0.79 to 0.99. Synonymous variants: 118 observed, 107.12 expected, observed/expected ratio (o/e) 1.1, 90% interval 0.95 to 1.28.
Homologues: Orthologues: chimpanzee SAMD10 (100% identical), macaque SAMD10 (98% identical), guinea pig SAMD10 (95% identical), mouse Samd10 (92% identical), rat Samd10 (84% identical), pig SAMD10 (76% identical), tropical clawed frog SAMD10 (59% identical), zebrafish samd10b (57% identical), zebrafish samd10a (53% identical), Drosophila melanogaster ave (17% identical), Caenorhabditis elegans ave-1 (15% identical). Paralogues in human: SAMD12 (35% identical).